RNU6-1114P (RNA, U6 small nuclear 1114, pseudogene)
Gene: Small nuclear RNA gene on chromosome 6 (16,205,014 to 16,205,120, forward strand). Ensembl gene ENSG00000251831.
Homologues: Orthologues: chimpanzee U6 (97% identical), macaque U6 (83% identical), rat LOC120102571 (73% identical), pig U6 (70% identical), dog U6 (65% identical), mouse Gm55402 (46% identical). Paralogues in human: RNU6-116P (78% identical), RNU6-24P (78% identical), RNU6-336P (78% identical), RNU6-380P (78% identical), RNU6-431P (78% identical), RNU6-560P (78% identical), RNU6-838P (78% identical), RNU6-1024P (77% identical), RNU6-1060P (77% identical), RNU6-1091P (77% identical), RNU6-11P (77% identical), RNU6-1340P (77% identical), and 1283 more.